APOE (apolipoprotein E)
Diseases named in the same sentence as APOE in open-access papers (continued):
Sharing a sentence is not in itself a finding about the gene and the disease.
Alzheimer disease (continued). "Apolipoprotein (ApoE) is the major susceptibility gene for the common late-onset form of Alzheimer's disease and the presence of the ε4 allele increases the risk of developing AD." (PMID 21755005, 2011). "Inheritance of the Apolipoprotein E (APOE) ε4 allele is the strongest known genetic risk factor for late onset Alzheimer disease (AD)." (PMID 21297948, 2011). "The apolipoprotein E (APOE) ε4 allele has been reported to be a risk factor for Alzheimer's disease (AD)." (PMID 21552550, 2011). "Three single nucleotide polymorphisms (SNPs) -491A>T, -219T>G and +113G>C in the regulatory region of human apolipoprotein E gene (APOE) change the promoter activity and are associated with a wide variety of disorders including Alzheimer disease (AD)." (PMID 21549015, 2011). "As an example, we can examine data for the role of the ε4 allele of the APOE gene in Alzheimer’s disease (AD)." (PMID 22649660, 2010). "Alleles of apolipoprotein E (APOE) are the major genetic risk factor for late onset Alzheimer's Disease (LOAD)." (PMID 20822524, 2010). "APOE variants are the single largest genetic factors impacting late onset Alzheimer Disease (LOAD), the most common neurodegenerative disease." (PMID 20822524, 2010). "Carriers of the apolipoprotein E (APOE) ε4 allele are at increased risk of late onset Alzheimer's disease." (PMID 20515477, 2010). "Apolipoprotein E (apoE) is a major cholesterol transport protein found in association with brain amyloid from Alzheimer's disease (AD) patients and the ε4 allele of apoE is a genetic risk factor for AD." (PMID 21034469, 2010). "Apolipoprotein-E (apoE) plays important roles in neurobiology and the apoE4 isoform increases risk for Alzheimer's disease (AD)." (PMID 20170526, 2010). "Alzheimer's disease (AD) is common and highly heritable with many genes and gene variants associated with AD in one or more studies, including APOE ε2/ε3/ε4." (PMID 20932310, 2010). "Apolipoprotein E (ApoE) and β-amyloid aggregates, associated with Alzheimer's disease, have been found in AMD-related macular drusen." (PMID 19551904, 2009). "Let us take the potential interaction in risk of Alzheimer's disease (AD) between the ε4 allele of apolipoprotein E (APOE4) and the GG genotype of the C/G polymorphism (rs638405) in exon 5 of the β-site APP-cleaving enzyme (BACE1)." (PMID 19527493, 2009). "The APOE ε4 allele has also been associated with early age-at-onset of Alzheimer’s Disease (AD) in a dose-dependent manner." (PMID 19421411, 2009). "More than a decade ago, the allelic variation of apolipoprotein E (apoE) was associated with an altered risk of Alzheimer's disease (AD) development." (PMID 19725929, 2009). "A gene implicated in Alzheimer's disease, APOE, was under positive selection along the hominid lineage." (PMID 18837980, 2008). "The APOE ε4 allele is the only consistently identified risk factor for late onset Alzheimer's disease (LOAD)." (PMID 18416843, 2008). "While the evidence of an association between the apolipoprotein E (APOE) *E4 allele and Alzheimer's disease is very strong, the effect of the *E4 allele on cognitive decline in the general population is more equivocal." (PMID 18620605, 2008). "The association of this SNP with risk of Alzheimer's disease and the presence of particular pathological features seems to be linked with the apolipoprotein E (APOE) genotype, but shows variability amongst populations tested." (PMID 18426579, 2008). "The notable exception is that of Alzheimer’s disease, where whole genome SNP association studies confirm that the apolipoprotein E (ApoE) locus confers the largest genetic susceptibility to AD." (PMID 19578496, 2008). "Carrying the APOE ε4 allele is a risk factor for early onset Alzheimer's disease (AD), and is the only consistently identified risk factor for late-onset Alzheimer's disease (LOAD)." (PMID 18416843, 2008).
Alzheimer disease (continued). "There is clear evidence that the presence of the apolipoprotein E4 allele (APOE *E4) is associated with increased risk of Alzheimer's Disease (AD)." (PMID 18620605, 2008). "Animal studies suggest that brain apolipoprotein E (apoE) levels influence amyloid-β (Aβ) deposition and thus risk for Alzheimer's disease (AD)." (PMID 17430597, 2007). "For example, a GWA study of 502,627 SNPs in 1086 cases of late-onset Alzheimer’s disease and controls verified the well established APOE susceptibility gene." (PMID 19662211, 2007). "The involvement of APOE polymorphisms in lipid metabolism, Alzheimer's disease, and a host of cardiovascular and cerebrovascular diseases imply pleiotropic effects of the gene." (PMID 17672902, 2007). "This fact is consistent with the association of ApoE with late onset Alzheimer's Disease and recent association results for age-related macular degeneration." (PMID 17634103, 2007). "Variants of the apolipoprotein E (APOE) gene have been associated with Alzheimer's disease, lipid disorders and cardiovascular disease." (PMID 17672902, 2007). "The presence of the apolipoprotein E (APOE) ε4 allele is a major risk factor for the development of Alzheimer's disease (AD), and has been associated with metabolic brain changes several years before the onset of typical AD symptoms." (PMID 16412236, 2006). "Apolipoprotein E (ApoE) genotype, the major genetic risk factor in sporadic late-onset Alzheimer Disease (AD), modulates cerebral perfusion in late middle-age cognitively normal subjects." (PMID 16930470, 2006). "ApoE isoform-specific modulation of several pathogenic processes, in addition to amyloid β metabolism in Alzheimer's disease, have been proposed: one of these is innate immune response by glia." (PMID 16603079, 2006). "Apolipoprotein E (ApoE) is established as the major genetic risk factor in sporadic late-onset Alzheimer Disease (AD), which is mainly characterised by memory impairment." (PMID 16930470, 2006). "Family history of dementia and the apolipoprotein E (APOE) genotype are significant risk factors for the development of Alzheimer's disease (AD)." (PMID 16412236, 2006). "The apolipoprotein E ε4 allele contributes to the genetic susceptibility underlying a large proportion (~40–60%) of typical, sporadic Alzheimer disease." (PMID 15312232, 2004). "The full impact of APOE4 (apolipoprotein E4), the strongest genetic risk factor for Alzheimer's disease (AD), on neuronal and network function remains unclear, particularly during early preclinical stages of disease." (PMID 41933197, 2026). "Apolipoprotein E ε4 (APOE4) is the strongest genetic risk factor for late-onset Alzheimer's disease (AD), yet whether its pathogenic effects are driven by HDL lipidation state or by elevated APOE4 levels in the CNS remains unclear." (PMID 42078865, 2026). "The APOE locus is the strongest genetic factor for Alzheimer's disease, with ε4 increasing and ε2 decreasing risk, yet the basis of these opposing effects remains unclear." (PMID 42141098, 2026). "Apolipoprotein E (APOE) ε4 is the strongest genetic risk factor for Alzheimer's disease (AD)." (PMID 41642643, 2026). "The apolipoprotein E (APOE) ε4 allele is the primary genetic driver of late-onset Alzheimer's disease (AD), a complex neurodegenerative disorder characterized by the interplay of amyloid-β (Aβ) accumulation, tau pathology, neuroinflammation, and lipid metabolism dysfunction." (PMID 42094593, 2026). "Variation in the APOE gene strongly affects Alzheimer’s disease (AD) risk." (PMID 41522467, 2026). "We examined whether diet quality is associated with executive function (EF) in middle-aged women with a family history of Alzheimer's disease (AD) and whether this is moderated by a genetic AD risk factor, APOE-ε4 allele carriage." (PMID 42267153, 2026).
Alzheimer disease (continued). "Anti-amyloid therapies for Alzheimer's disease (AD) modestly slow cognitive decline but carry significant risk of amyloid-related imaging abnormalities (ARIAs), brain swelling, and hemorrhage, particularly in apolipoprotein E ε4 carriers." (PMID 41950067, 2026). "Cognitive impairment varies across sporadic Parkinson's disease (PD) and the common genetic subtypes glucocerebrosidase (GBA1) and leucine-rich repeat kinase 2 (LRRK2) PD and is influenced by Apolipoprotein E (APOE) polymorphisms and Alzheimer's disease (AD) co-pathology." (PMID 41730900, 2026). "At the same time, Alzheimer's disease polygenic risk scores (AD-PRS) can capture non-APOE common-variant burden across lipid transport, endosomal trafficking, innate immune signaling, complement activity, microglial regulation, mitochondrial stress, and neurovascular integrity." (PMID 42199314, 2026). "APOE-ε4 is a major genetic risk factor for Alzheimer’s disease, so the exercise-augmented hippocampal perfusion might be a neuro-protective mechanism in a group vulnerable to a neurodegenerative condition." (PMID 40903847, 2025). "Moreover, sleep disturbances and neuroinflammation also share common risk factors with Alzheimer’s disease, such as apolipoprotein E ε4 (APOE ε4) genotype and ageing." (PMID 41268178, 2025). "Indeed, C. elegans models of Alzheimer disease, which carry a mutation in the gene orthologous to human amyloid precursor protein and apolipoprotein E, can be used to model a decline in locomotion." (PMID 40692178, 2025). "The APOE ε4 allele is among the best-established genetic risk factor for Alzheimer’s disease." (PMID 40791670, 2025). "A highly relevant finding on genetic susceptibility has shown that the genotype APOE4 of apolipoprotein E is not only a risk factor for Alzheimer’s Disease, but also that APOE4 carriers, of Amerindian origin, can accumulate more mercury and are therefore at even higher neurological risk." (PMID 40756479, 2025). "Apolipoprotein E4 (APOE4) is the leading genetic risk factor for Alzheimer’s disease." (PMID 40541173, 2025). "Furthermore, endotoxin binding to apolipoprotein E promotes amyloid-β and tau aggregation, increasing Alzheimer’s disease susceptibility." (PMID 40824609, 2025). "In addition to age, the genetic background plays a significant role in Alzheimer’s disease risk, with the APOE ε4 allele being the major genetic susceptibility factor for late-onset AD." (PMID 40076562, 2025). "For instance, the presence of the APOE ε4 allele is a well-established risk factor for cognitive decline in Alzheimer’s disease, and its consistent association with MBI across populations suggests a shared biological pathway that warrants further investigation." (PMID 40657582, 2025). "Concurrently, we employed seven machine learning methods, we initially screened out 315 hub genes, and then employed (SVM, LASSO, KNN, XGB, GBM, C5.0, NNET) to mine diagnostic genes differentiating APOE ε3/ε4 female healthy controls from APOE ε3/ε4 female Alzheimer’s disease patients." (PMID 41409615, 2025). "Genomic profiling was performed in the iPSC for neurodegenerative risk genes, such as APOE, and polygenic risk scores (PRSs) were calculated to estimate the overall burden of genetic factors associated with African ancestries in Alzheimer's disease (AD) and other neurodegenerative diseases." (PMID 40219788, 2025). "Particularly, individuals with the APOE e4 genotype may have an increased risk of Alzheimer's disease and greater severity of cognitive impairments, potentially due to enhanced IL-6 expression." (PMID 39981345, 2025). "Microglia exposed to the serum of future Alzheimer's disease patients from the 3C Study displayed an increased phagocytic uptake compared with the serum of matched controls, depending on the presence of the apolipoprotein E ε4 allele in the Alzheimer's disease patients." (PMID 40537026, 2025).
Alzheimer disease (continued). "Our study revealed that Alzheimer’s disease patients carrying the APOE ε4 homozygous allele exhibited significantly higher ARIA-E incidence following lecanemab/donanemab treatment compared to non-carriers, with a relatively attenuated risk increase observed in the lecanemab group." (PMID 40308765, 2025). "Age-related elevation of gonadotropins may contribute to cognitive decline, while apolipoprotein E epsilon 4 (APOE ε4) is an established risk factor for Alzheimer’s disease (AD)." (PMID 41180813, 2025). "The E4 allele of apolipoprotein E (ApoE4), a risk factor for Alzheimer’s disease, increases ER-mitochondria communication and activity in human fibroblast and primary mouse neurons, which could contribute to the disease." (PMID 40302938, 2025). "Recent evidence suggests that the interaction between APOE and heparan sulfate proteoglycans (HSPGs) may be relevant to the predisposition to, protection from, and potential treatment and prevention of Alzheimer’s disease (AD)." (PMID 39379683, 2025). "Presenilin 1 (PSEN1) and amyloid precursor protein (APP) are well-established genetic factors associated with early-onset familial Alzheimer’s disease (EOFAD), whereas apolipoprotein E4 (APOE4) is a recognized genetic risk factor for sporadic late-onset Alzheimer’s disease (LOAD)." (PMID 40244244, 2025). "APOE play an important role in senescent, tumor immunity, and tumor prognosis, and Polymorphisms in the APOE gene have been strongly associated with age-related diseases such as Alzheimer’s disease." (PMID 40292294, 2025). "Additionally, APOE has been associated with transactive response DNA-binding protein 43 (TDP-43) pathology in Alzheimer’s disease brains." (PMID 40382659, 2025). "APOE polymorphism affects the risk of occurrence and the rate of progression in several neurodegenerative diseases including Alzheimer’s disease, primary tauopathies, α-synucleinopathy, and age-related macular degeneration, but its role in prionoses remains unestablished." (PMID 41282061, 2025). "In Alzheimer’s disease (AD), personalized medicine helps predict risk and guide targeted treatments through APOE ε4 and other genetic variants, while in Parkinson’s Disease (PD), mutations in the GBA and LRRK2 genes influence disease course and therapy response." (PMID 41590228, 2025). "The link between the apolipoprotein E (APOE) E4 allele and cortical neurodegeneration is well known in Alzheimer's dementia and the pathological overlap between PD and Alzheimer's is well established, with tau and α‐synuclein deposition often found in combination." (PMID 40926580, 2025). "APOE ε4 is commonly and increasingly used for personalized medicine, as a direct-to-consumer test, and is also now a required part of risk counseling for amyloid-beta monoclonal antibodies for Alzheimer's disease." (PMID 41282305, 2025). "Apolipoprotein E4 (APOE4) is recognized as a major risk factor for disorders such as Alzheimer's disease and may play a role in the dysregulation of microglia in various neurodegenerative conditions." (PMID 41253293, 2025). "Notably, the ApoE-ε4 allele has been identified as a significant risk factor for conditions such as Alzheimer’s disease (AD) and multiple sclerosis (MS), with a dose-dependent effect on both the risk and age of onset." (PMID 40258814, 2025). "The impact of amyloid-β (Aβ) accumulation on regional brain atrophy in preclinical Alzheimer’s disease (AD), and its interaction with risk factors like sex and APOE-ε4 carriership, remains unclear." (PMID 41270680, 2025). "However, findings are not consistent with research showing an interaction between depression and APOE genotype on risk of Alzheimer's disease, in which strongest associations were observed in participants with the APOE‐ε4 allele." (PMID 40581914, 2025). "Age, sex, and apolipoprotein E (APOE) genotype are major risk factors for Alzheimer's disease (AD)." (PMID 40883957, 2025).
Alzheimer disease (continued). "Here, we investigated whether apolipoprotein E4 (ApoE4), the major genetic risk factor for Alzheimer disease, altered intracellular transport in human brain endothelial cells." (PMID 40845853, 2025). "In this article, we explore available data and hypothesise that cerebral malaria might be linked to APOE-mediated amyloidosis, one of the pathological processes associated with Alzheimer’s disease." (PMID 39023792, 2025). "We suspect that the nominal association between PDC and the Alzheimer’s disease polygenic score may be largely driven by pleiotropic effects of APOE-ε4, which is a major genetic risk factor for both Alzheimer's disease and altered lipid metabolism." (PMID 40696379, 2025). "Finally, knock-in mouse models that express the human APOE4 allele, related with the late-onset of Alzheimer disease, have shown that the microglia of aged animals strongly express APOE." (PMID 40028333, 2025). "Additionally, APOE was genotyped for e3/e3 alleles, corresponding to normal late-onset Alzheimer disease risk." (PMID 40569594, 2025). "Additionally, a study on Alzheimer’s disease (AD) suggested that carriers of the APOE ε4 allele exhibit higher levels of oxidative stress and decreased antioxidant activity in the hippocampal region of the brain." (PMID 40688943, 2025). "Apathy and APOE ε4 genotype are risk factors for developing Alzheimer’s disease dementia (ADD)." (PMID 40227643, 2025). "Furthermore, Apolipoprotein E (ApoE) is a late-onset genetic risk factor for dementia, which is strongly associated with Alzheimer’s disease." (PMID 41032496, 2025). "Differences in DNA methylation have been reported both in blood and brain tissue of Alzheimer’s disease cases compared to healthy controls, especially in gene regions associated with AD pathology, including apolipoprotein E (ApoE) and the amyloid precursor protein (APP) but also in other genes." (PMID 39853302, 2025). "Finally, a further study showed an interaction between depression and APOE genotype on risk of Alzheimer's disease, in which the strongest associations were observed in participants with the APOE‐ε4 allele." (PMID 40581914, 2025). "The APOE gene has three different alleles associated with Alzheimer's disease (AD)." (PMID 40440483, 2025). "The APOE genotype is one of the most important markers of risk for Alzheimer’s disease; there are three isoforms that represent a higher or lower risk in the development of Alzheimer’s disease: ε2 (protecting allele), ε3 (neutral), and ε4 (highest risk)." (PMID 40429722, 2025). "Genetic components such as the APOE ε4 allele, which is responsible for Alzheimer’s disease, and mutations in LRRK2, which are responsible for Parkinson’s disease, are now facilitating the development of individualized approaches for neurosurgical or pharmacological treatments." (PMID 40806492, 2025). "Given the established influence of genetic factors such as APOE on dementia risk, we examined whether the inclusion of polygenic risk scores for Alzheimer’s disease modified our findings." (PMID 41211101, 2025). "The APOE genotype may be a genetic risk factor for neurodegenerative diseases other than Alzheimer's disease." (PMID 40672452, 2025). "We evaluated both main effects and interactions with Alzheimer’s disease risk factors, such as older age, female sex and the apoliporoptein E (APOE)-ɛ4 allele, in a priori defined regions of interest and further examined the associations on the whole-brain using voxel-wise regressions." (PMID 39723106, 2025). "These include studies involving familial Alzheimer’s disease causing mutants of Presenilin-1 and − 2 and the amyloid precursor protein (APP), and studies on the effects of ε4 allele of apolipoprotein E (ApoE4) which is a major risk factor for Alzheimer’s disease." (PMID 40045432, 2025). "APOE-ε4 allele is well known as a key determinant of Alzheimer’s disease and cognitive impairment." (PMID 41026459, 2025).